MAFTRR (MAF transcriptional regulator RNA)
Synonyms: linc-MAF-4; lincMAF4
Gene: Long non-coding RNA gene on chromosome 16 (79,605,850 to 79,770,651, reverse strand). Ensembl gene ENSG00000261390.
Diseases named in the same sentence as MAFTRR in open-access papers:
MAFTRR is named in the same sentence as 9 diseases in open-access papers, as found by Europe PMC text mining. Sharing a sentence is not in itself a finding about the gene and the disease. The quoted sentences say what the papers report.
autoimmune disease (1 paper, 2021). A disorder resulting from loss of function or tissue destruction of an organ or multiple organs, arising from humoral or cellular immune responses of the individual to their own tissue constituents. "As a typical organ-specific autoimmune disease, we further investigated the levels of MAFTRR and IFNG in the thyroid tissues." (PMID 34869781, 2021).
goiter (1 paper, 2021). Enlargement of the thyroid gland usually caused by lack of iodine in the diet, hyperthyroidism, or thyroid nodules. "Results showed that the relative expression of MAFTRR and IFNG in the thyroid glands from the HT patients were higher than that from patients with simple goiter." (PMID 34869781, 2021).
gout (1 paper, 2018). A condition characterized by painful swelling of the joints, which is caused by deposition of urate crystals. "The serum urate-raising and gout risk allele rs7188445_G associates with increased MAFTRR expression and lowered EHHADH expression." (PMID 30719032, 2018).
Hashimoto thyroiditis (1 paper, 2021). An autoimmune disorder caused by the production of autoantibodies against thyroid tissue. "This research was aimed at investigating the expression of MAFTRR in Hashimoto's thyroiditis (HT) as well as the correlation between MAFTRR and Th1 cells." (PMID 34869781, 2021). "However, the effect of MAFTRR on the pathogenesis of Hashimoto's thyroiditis (HT) remains unclear." (PMID 34869781, 2021).
multiple sclerosis (1 paper, 2018). A progressive autoimmune disorder affecting the central nervous system resulting in demyelination. "An inverse relationship between MAFTRR levels and MAF expression has previously been identified in patients with multiple sclerosis, whereby higher levels of MAFTRR in CD4+ T lymphocyte cells lowers expression of MAF." (PMID 30719032, 2018).
myeloma (1 paper, 2017). "Two homozygous deletions each in myeloma and sarcoma targeted MAFTRR (MAF transcriptional regulator RNA), a long intergenic noncoding RNA gene." (PMID 29089486, 2017).
sarcoma (1 paper, 2017). A usually aggressive malignant neoplasm of the soft tissue or bone. "Note that one homozygous deletion in sarcoma abolishes both MAF and MAFTRR, suggesting MAFTRR may still have other functions." (PMID 29089486, 2017).
tumor (2 papers, 2017 to 2023). "Here, the authors conduct pan-cancer analyses and apply statistical modelling to identify 27 candidate tumour suppressors, including MAFTRR, KIAA1551, and IGF2BP2." (PMID 29089486, 2017). "Other candidate tumour suppressors, such as MAFTRR, KIAA1551, and IGF2BP2, are novel." (PMID 29089486, 2017). "Our proposed tumour suppressors include genes previously suggested to play a role in oncogenesis (e.g., MGMT and USP44), as well as novel candidates (e.g., KIAA1551, CASP3, and MAFTRR)." (PMID 29089486, 2017).
MAFTRR also shares sentences with these, for which no sentence is quoted: hypothyroidism (1 paper).